EPHB2 (EPH receptor B2)
Diseases named in the same sentence as EPHB2 in open-access papers (continued):
Sharing a sentence is not in itself a finding about the gene and the disease.
adenoma (13 papers, 2006 to 2025). A neoplasm arising from the epithelium. "In contrast, despite the maintenance of overt nuclear expression of β-catenin, EPHB2 expression was lost in the adenoma-CRC transition." (PMID 38651144, 2024). "Adenoma areas containing Paneth cells display increased vessel density in the lamina propria and higher levels of the stem cell marker EphB2." (PMID 34831152, 2021). "Increased expression of EPHB2 in adenomas and adenocarcinomas compared to normal tissues was confirmed by immunohistochemistry and was clearly localised to the epithelial tumour tissue." (PMID 26367378, 2015). "Indeed, EphB2 can drive proliferation in the normal colon-adenoma sequence and function as a tumor suppressor in CRC, and this because EphB2 involves separate signaling pathways to regulate cell proliferation and cell migration." (PMID 38651144, 2024). "In contrast, in C57BL mice, EphB2 was expressed in normal mucosa, adenoma and cancer." (PMID 35949596, 2022). "The reduction of the EPHB2 levels has been found to correlate with the degree of malignancy, as a significant decrease in number of EPHB2 positive cells and in staining intensity has been observed at the adenoma-carcinoma transition." (PMID 16740153, 2006). "While cells in early lesions of dysplastic crypts and small adenomas, like normal crypt progenitor cells, were found to express EphB2, high-grade tumor areas contained EphB2-negative cells." (PMID 38391938, 2024). "Supporting a role for Jag1 in adenoma formation and by extension in tumor-initiating cell (TIC) activity, Jag1 KO adenomas expressed reduced levels of Lgr5, Bmi1, Ephb2, c-Myc, Sox9, and Cd133 compared to the Jag1 WT, as determined by qRT-PCR and in situ hybridization (ISH)." (PMID 30065304, 2018). "Interestingly, in KKAy mice, EphB2 was expressed at lower levels in adenomas, and its expression was not detectable in cancer." (PMID 35949596, 2022). "The demonstration that Paneth cell accumulation specifically in the adenoma samples correlating with higher levels of nuclear β-catenin and ICN1, and differential EPHB2 distribution led us to study the possibility that Paneth cells may serve as a prognosis marker in low-grade tumor patients." (PMID 34831152, 2021).
glioblastoma (12 papers, 2015 to 2025). The most malignant astrocytic tumor (WHO grade IV). "We previously generated a mAb against EphB2, designated Eb2Mab-12 (mouse IgG1, κ), by immunizing mice with EphB2-overexpressed glioblastoma LN229." (PMID 40943224, 2025). "We previously developed an anti-EphB2 mAb, Eb2Mab-12 (IgG1, kappa), by immunizing mice with EphB2-overexpressed glioblastoma." (PMID 40943224, 2025). "The results revealed that EphA2, EphB2, EphB3, and EphB4 were significantly upregulated, while EphA4 and EphB6 were significantly downregulated in glioblastoma than normal brain tissues, respectively." (PMID 37146061, 2023). "Two of the ephrin class RTKs, EPHA3, and EPHB2, also showed overexpression in scattered cases across the glioblastoma subgroups but more prominently in the Multi-RTK and PDGFRA subgroups, respectively." (PMID 34572759, 2021). "Together with new targets revealed in this study, such as EPHB2, these RTKs also warrant consideration for glioblastoma therapy." (PMID 34572759, 2021). "We further validated the interaction between Gulp1 and EphB2 using U251 glioblastoma cells that endogenously express both proteins." (PMID 31409653, 2019). "In glioblastoma multiforme (GBM), EphB2 overexpression correlated to poor overall survival in GBM patients." (PMID 35223830, 2022). "EphB2 has also been shown to play a critical role in medulloblastoma, ependymoma, and glioblastoma (GBM) by other research groups." (PMID 28360821, 2017).
medulloblastoma (12 papers, 2015 to 2025). A malignant, invasive embryonal neoplasm arising from the cerebellum. "EPHB1 and EPHB3 are overexpressed in rhabdomyosarcoma tumor cells, while EPHB2 high-level expression has been reported in medulloblastoma tumor tissue samples, in NF2-deficient meningioma cell lines, and rhabdomyosarcoma tumor cells." (PMID 38612645, 2024). "Elevated expression of EphA2, EphB2, and EphB4 in medulloblastoma cell line is linked to ephrin-B1 mediated invasion." (PMID 29682554, 2018). "After observing the EphB2-knockdown mediated radiosensitization effects in vitro, we investigated the underlying mechanism by which knockdown of EphB2 enhanced radiosensitivity of medulloblastoma cells." (PMID 28360821, 2017). "EphB2 is upregulated in primary medulloblastomas compared to normal cerebellum, with high expression observed in DAOY and Res-300 cell lines." (PMID 41200151, 2025). "We should note, though, that for certain EPH/ephrin members, such as EPHB1 in medulloblastoma and EPHB2 in ependymoma, the reported variable levels of expression render the characterization of their role in tumorigenesis ambiguous." (PMID 38612645, 2024). "For example, the medulloblastoma cell lines with high expression of EphB2 were stimulated by ephrin-B1, the cell adhesion ability in vitro was significantly decreased, and the invasion ability was increased." (PMID 35223830, 2022). "Higher expression levels of EphB2 have also been measured in medulloblastoma samples, concomitant with decreased cell adhesion and increased invasion when EphB2 was stimulated with ephrin-B1." (PMID 33430066, 2021). "EphB2 has been shown to play a pivotal role in the activation of pathways involved in cell adhesion and invasion in medulloblastoma." (PMID 33050158, 2020). "EphB2 and its ligand ephrin-B1 have been shown to be highly expressed in medulloblastoma tissue samples, and EphA2, EphB2, and EphB4 are overexpressed in medulloblastoma cell lines." (PMID 33050158, 2020). "The Eph/ephrin signaling system plays a key role in the invasion of medulloblastoma, and EPH Receptor B2, EphB2, was found to be critical for invasion of pediatric medulloblastoma." (PMID 32508873, 2020). "EPHB2 affects cell viability in medulloblastoma in part by promotion of the G2/M phase of the cell cycle." (PMID 32102656, 2020). "Transcriptome sequencing / real time RT-PCR / western blot analysis showed downregulation of RAB22A, M6PR, EZR, EPHB2, upon miR-204 expression in medulloblastoma cells as well." (PMID 30944042, 2019). "We validated the expression of EphB2 in two different human medulloblastoma cell lines DAOY and UW228." (PMID 28360821, 2017). "The key observation in our experiments is the significant reduction in invasive potential of medulloblastoma cells following combined inhibition of EphB2 knockdown with radiation compared to other groups." (PMID 28360821, 2017). "These migrating cells were characterized by upregulation of EphB2 as shown by qPCR analysis in DAOY medulloblastoma cells." (PMID 28360821, 2017). "To investigate the functional role of EphB2 in our in vitro model system, we transiently transfected medulloblastoma cells with either an EphB2-siRNA or a control NS-siRNA and analyzed the knockdown efficiency at protein level." (PMID 28360821, 2017). "In the present study, we investigated, for the first time, the effects of combined EphB2 knockdown and radiation on cell growth, viability, and invasiveness of medulloblastoma cells." (PMID 28360821, 2017). "Although variability can be seen across the different datasets, similar trends were observed with all the four medulloblastoma subtypes showing elevated expression of EphB2 compared to the normal cerebellum." (PMID 28360821, 2017). "The radiosensitization effect following EphB2 knockdown was determined by clonogenic assay in human medulloblastoma cells." (PMID 28360821, 2017).
medulloblastoma (continued). "We analyzed transcriptomic data performed on a cohort of medulloblastoma patients obtained from Children’s Hospital Colorado and found that EphB2 is significantly overexpressed in these samples compared to the non-malignant brain samples." (PMID 28360821, 2017). "We also found that the combined approach of EphB2 knockdown and radiation exposure significantly reduced overall cell viability in medulloblastoma cells compared to control groups." (PMID 28360821, 2017). "Regardless, our results emphasize the importance of combined EphB2 downregulation with radiation as a potential therapeutic approach to achieve anti-tumorigenic effects in pediatric medulloblastoma." (PMID 28360821, 2017). "Higher EphB2 levels are present in medulloblastoma patient samples as compared to the normal cerebellum." (PMID 28360821, 2017). "In conclusion, our data shed light on the efficacy of strategy involving combined EphB2-knockdown with radiation in medulloblastoma." (PMID 28360821, 2017). "EphB2 expression was also high across different medulloblastoma subgroups compared to normal cerebellum." (PMID 28360821, 2017). "We next investigated the effect of EphB2 knockdown followed by radiation on medulloblastoma cell invasion in an electrical impedance-based assay." (PMID 28360821, 2017). "In the analysis performed on medulloblastoma patients, we observed a variable but significant increase in the expression of EphB2 across the different subgroups compared to the normal cerebellum." (PMID 28360821, 2017). "We observed that EphB2 is expressed in both medulloblastoma cell lines and patient samples and its downregulation sensitized these cells to radiation as evident by decreased clonogenic survival fractions." (PMID 28360821, 2017). "Moreover, subsequent studies have confirmed the crucial role of EPH/ephrin signaling in the medulloblastoma metastatic capacity; EPHB2 and ephrin-B1—except for being overexpressed—were also found to associate with invasive and metastatic tumor subtypes." (PMID 38612645, 2024). "EphB2 knockdown combined with radiation exposure induced G2/M cell cycle arrest, reduced clonogenic survival fractions, inhibited medulloblastoma cell viability, and reduced medulloblastoma cell invasion." (PMID 35223830, 2022). "Moreover, EPHB2 mediated malignant progression of medulloblastoma by regulating ERK, P38 and mTOR pathway." (PMID 36032135, 2022). "This is the first study to show the impact of EphB2 inhibition in combination with radiation in medulloblastoma cells and provides a rational basis for targeted inhibition of the EphB2 receptor as a potential radiosensitization strategy in medulloblastoma." (PMID 28360821, 2017). "However, EphB2 knockdown approach in combination with radiation, resulted in a significant reduction in viability as observed in both the medulloblastoma cell lines." (PMID 28360821, 2017). "In the current study, we investigated whether EphB2 knockdown in combination with radiation can alter invasiveness and decrease medulloblastoma tumor growth or viability in vitro." (PMID 28360821, 2017). "However, when the EphB2-siRNA transfected cells were combined with an optimal dose of radiation, a significant decrease in cell viability was observed in both the medulloblastoma cell lines." (PMID 28360821, 2017). "In addition to EphB2, other studies in the literature have shown that medulloblastoma cells when exposed to radiation exhibit enhanced cell invasion." (PMID 28360821, 2017). "However, ephrin-A5 is a promiscuous ligand that binds to multiple other Eph A and B receptors including EphB1 and EphB2, both of which are present in medulloblastoma tumors." (PMID 26345456, 2015). "Therefore, in this study, we sought to address whether the combination of EphB2 knockdown with radiation would negate any pro-invasive effects radiation may have on medulloblastoma cells." (PMID 28360821, 2017).
medulloblastoma (continued). "Regarding EPH/ephrin members’ expression, upregulation of EPHB2 and ephrin-B1 has been reported in tumor samples compared to normal cerebellum, while EPHA2, EPHB2, and EPHB4 showed overexpression in medulloblastoma cell lines." (PMID 38612645, 2024). "It is therefore not surprising that EphB2 knockdown in medulloblastoma cells combined with radiation exposure led to significant reduction of cell viability and invasion." (PMID 29682554, 2018).
Cognitive impairment (11 papers, 2011 to 2025). Abnormal cognition is characterized by deficits in thinking, reasoning, or remembering. "EPHB2 deficiency results in depression-like behavior and cognitive impairment in mice, whereas EPHB2 overexpression restores synaptic NMDAR targeting and rescues memory deficits in AD models." (PMID 40914484, 2025). "Nevertheless, it is not well understood how does loss of EphB2 mediate depression and associated cognitive deficits." (PMID 30131699, 2018). "To better understand how EphB2 mutation causes depression and the cognitive impairment, we used a mouse model engineered to have an inactivating mutation in the entire EphB2 receptor." (PMID 30131699, 2018). "While N-methyl-D-aspartate (NMDA) receptor is involved in regulating memory formation and neurogenesis in adult animal, it remains unclear how NMDA receptor subtypes mediate depression and cognitive deficits caused by EphB2 loss." (PMID 30131699, 2018). "Age‐related loss of EphB2 may contribute to cognitive deficits by accelerating this deterioration." (PMID 26799631, 2016). "Dysfunction of EPHB2 and its ligand EFNB1 has been implicated in brain disorders, such as cognition disorders and depression." (PMID 31920518, 2019). "The fact that NR2B antagonist prevented depression-like behaviors and cognitive impairment in EphB2 KO mice further confirms the involvement of NMDA receptor 2B in EphB2 mediated behavioral abnormalities." (PMID 30131699, 2018). "Overall, we demonstrated that reversing EphB2 expression by lentiviral vector in the dorsal hippocampus rescued cognitive deficits, the phosphorylation and surface expression of GluN2B-containing NMDA receptors in APP/PS1 transgenic mice." (PMID 28358367, 2017). "A study of TG mice reported that Ephb2 KO mice exhibited cognitive impairment in contextual learning and that Ephb2 might regulate morphine-dependent learning and memory." (PMID 39002057, 2025). "EphB2 may thus be as an important candidate target for treating psychiatric and cognitive disorders." (PMID 30131699, 2018). "Furthermore, it was shown induction of the EphB2 expression in the dentate gyrus prevented the cognitive deficits and LTP impairments in mice model of AD." (PMID 29954063, 2018). "At least four members of the Eph receptor family including EphA4, EphB1, EphB2, and EphB3 are highly expressed in the prefrontal cortex, hippocampus and amygdala, whose functions are closely related to emotional and cognitive disorders, such as depression, anxiety, and memory deficits." (PMID 30131699, 2018). "Indeed, EphB2 is depleted in the brains of transgenic hAPP mice and AD patients, and replacement of EphB2 reverses cognitive impairment in hAPP mice." (PMID 21871088, 2011). "The subsequently decreased pCREB and BDNF expression in the hippocampus of EphB2 KO mice supports the hypothesis that the downstream molecules genetically interact with EphB2 to regulate neurogenesis and suppress depression-like behaviors and cognitive deficits." (PMID 30131699, 2018). "EPHB2 TNF-α/nuclear factor-kappa B signaling has been reported to worsen cognitive impairment." (PMID 35646066, 2022). "The results of EphB2 degradation are the impairment of NMDAR functioning and cognitive deficits." (PMID 29954063, 2018). "However, the conclusion is that interactions between EPHB2, OPRM1, and PER2 lead to cognitive impairment, which is not sufficiently supported by the observed changes in expression levels." (PMID 39002057, 2025).
depression (11 papers, 2017 to 2025). "It is well known that EPHB2 deficiency has been related to depression-like conditions and memory impairments in animal studies." (PMID 39518903, 2024). "EPHB2 deficiency has been linked to depression-like behaviors and memory impairments in animal studies." (PMID 35523767, 2022). "Our results extend these findings for the first time and suggested that deficiency of EphB2 was responsible for both depression-like behaviors and for related learning and memory deficits." (PMID 30131699, 2018). "We further show that pharmacological inhibition of NR2B by Ro25-6981 reversed EphB2 knockout-induced depression-like behaviors and associated memory impairment." (PMID 30131699, 2018). "Given several key proteins within the pathway, such as Ephrin-B1 (EFNB1) and EPHB2, Ephrin receptor signaling may participate in inflammation-associated depression." (PMID 31920518, 2019). "IL-6, for example, is elevated in microglia following EphB2 treatment but also in the brains of PLWH and is associated with HIV induced depression." (PMID 40588746, 2025). "There is also a close link between EphB2 inactivation and depression-like behaviors, memory impairment, and adult hippocampal neurogenesis defects." (PMID 34095115, 2021). "In mice affected by chronic social stress, the expression level of EphB2 and its downstream molecules in mPFC are reduced, and the specific cleavage of the EphB2 receptor can increase sensitivity to stress and induce depression-like behavior." (PMID 33613615, 2020). "Even in other subtypes of depression animal models, EPHB2 was preliminarily found to regulate neuronal development, NMDAR function, and synaptic plasticity of the hippocampus and PFC." (PMID 31920518, 2019). "Understanding the role of EphB2 and GluN2A in depression provides novel molecular intervention targets for future treatment." (PMID 31920518, 2019). "The present study shows that EphB2 inactivation results in depression-like behaviors, memory impairment and defects of adult hippocampal neurogenesis." (PMID 30131699, 2018). "Following recognition of EphB2 knockout-induced depression-like behaviors, learning and memory deficits induced by EphB2 knockout were also found in the water maze test, as mice showed longer latency to catch the platform during training blocks." (PMID 30131699, 2018). "These molecular, cellular and behavioral alterations induced by EphB2 inactivation were reversed by NR2B antagonist Ro25-6981, suggesting that EphB2 functions to prevent the progression of depression-like behavior and memory impairment by downregulating NR2B." (PMID 30131699, 2018). "In conclusion, our findings show that inactivating EphB2 produces depression-like behaviors and deficits in memory and cognitive processes." (PMID 30131699, 2018). "Here we show that EphB2 plays an important role in depression-like behaviors, cognitive and memory impairment by inactivating the gene using a knockout approach." (PMID 30131699, 2018). "Here we identified that overexpression of EphB2 with lentiviral vectors in dorsal hippocampus improved impaired memory deficits and anxiety or depression-like behaviors in APPswe/PS1-dE9 (APP/PS1) transgenic mice." (PMID 28358367, 2017). "Additionally, the deficiency in human APP/PS1 transgenic mice can be alleviated with overexpression of EPHB2 with improved impaired memory, depression, and anxiety-like behaviours." (PMID 37186582, 2023). "Understanding the role of EphB2 in depression and cognitive processes may provide novel molecular intervention targets and enable future treatment of major depressive disorder." (PMID 30131699, 2018). "Receptor tyrosine kinase EphB2 mediates development of the neurogenic niche of excitatory neurons, suggesting the possibility that its inactivation plays a role in neuropsychiatric disorders including depression and memory impairment." (PMID 30131699, 2018).
depression (continued). "Thus, we considered the possibility that hypothalamic-upregulated EPHB2 might facilitate the cluster of GluN2A via PDZ interaction with PSD-95 in the development of depression." (PMID 31920518, 2019).